HOXA6 (homeobox A6)
Description:
Sequence-specific transcription factor which is part of a developmental regulatory system that provides cells with specific positional identities on the anterior-posterior axis.
Synonyms: HOX1B; HOX1; HOX1.2
Tractability: PROTAC: ubiquitination databases record sites on it.
Gene: Protein-coding gene on chromosome 7 (27,145,396 to 27,150,603, reverse strand). Ensembl gene ENSG00000106006.
Subcellular location: Nucleus
Subcellular location (Human Protein Atlas): Nucleoplasm; Nuclear speckles
Pathways (Reactome):
Developmental Biology: Formation of the nephric duct
Gene Ontology:
Molecular function: sequence-specific double-stranded DNA binding; DNA-binding transcription factor activity, RNA polymerase II-specific; RNA polymerase II cis-regulatory region sequence-specific DNA binding; DNA binding; DNA-binding transcription factor activity
Biological process: anterior/posterior pattern specification; regulation of transcription by RNA polymerase II; regulation of DNA-templated transcription
Cellular component: nuclear speck; nucleoplasm; chromatin; nucleus
Genetic constraint (gnomAD): Loss-of-function variants: 19 observed, 24.86 expected, observed/expected ratio (o/e) 0.76, 90% interval 0.53 to 1.12. The upper end of that interval is the gene's LOEUF score, 1.12, which puts it in group 4 of 6, group 1 being the genes least tolerant of losing a copy. Missense variants: 346 observed, 336.86 expected, observed/expected ratio (o/e) 1.03, 90% interval 0.94 to 1.12. Synonymous variants: 140 observed, 144.38 expected, observed/expected ratio (o/e) 0.97, 90% interval 0.84 to 1.12.
Homologues: Orthologues: chimpanzee HOXA6 (100% identical), chimpanzee HOXA6 (99% identical), guinea pig HOXA6 (98% identical), dog HOXA6 (98% identical), mouse Hoxa6 (96% identical), macaque HOXA6 (79% identical), tropical clawed frog hoxa6 (73% identical). Paralogues in human: HOXB6 (52% identical), HOXC6 (43% identical), HOXB7 (39% identical), HOXA5 (38% identical), HOXA7 (38% identical), HOXB5 (36% identical), HOXB8 (34% identical), HOXC8 (33% identical), HOXD4 (33% identical), HOXD8 (33% identical), HOXA4 (31% identical), HOXC4 (31% identical), and 30 more.